ZNF235 (zinc finger protein 235)
Description:
May be involved in transcriptional regulation.
Synonyms: ZFP93; ZNF270; HZF6; ANF270
Tractability: PROTAC: ubiquitination databases record sites on it.
Gene: Protein-coding gene on chromosome 19 (44,228,729 to 44,305,046, reverse strand). Ensembl gene ENSG00000159917.
Subcellular location: Nucleus
Subcellular location (Human Protein Atlas): Nucleoplasm
Pathways (Reactome):
Gene expression (Transcription): Generic Transcription Pathway
Gene Ontology:
Molecular function: DNA-binding transcription factor activity; sequence-specific DNA binding
Biological process: negative regulation of DNA-templated transcription; regulation of DNA-templated transcription
Cellular component: nucleoplasm; nucleus
Genetic constraint (gnomAD): Loss-of-function variants: 33 observed, 41.91 expected, observed/expected ratio (o/e) 0.79, 90% interval 0.6 to 1.05. The upper end of that interval is the gene's LOEUF score, 1.05, which puts it in group 4 of 6, group 1 being the genes least tolerant of losing a copy. Missense variants: 753 observed, 896.81 expected, observed/expected ratio (o/e) 0.84, 90% interval 0.79 to 0.89. Synonymous variants: 287 observed, 301.14 expected, observed/expected ratio (o/e) 0.95, 90% interval 0.87 to 1.05.
Homologues: Orthologues: chimpanzee ZNF235 (99% identical), macaque ZNF235 (96% identical), guinea pig ZNF235 (76% identical), pig ZNF235 (74% identical). Paralogues in human: ZNF227 (50% identical), ZNF112 (43% identical), ZNF226 (42% identical), ZNF234 (41% identical), ZNF229 (41% identical), ZNF224 (41% identical), ZNF568 (40% identical), ZNF658 (40% identical), ZNF726 (40% identical), ZNF28 (40% identical), ZNF728 (40% identical), ZNF724 (39% identical), and 164 more.
Diseases named in the same sentence as ZNF235 in open-access papers:
ZNF235 is named in the same sentence as 1 disease in open-access papers, as found by Europe PMC text mining. Sharing a sentence is not in itself a finding about the gene and the disease.
ZNF235 shares sentences with these, for which no sentence is quoted: Zinc deficiency (1 paper).